RNU6-648P (RNA, U6 small nuclear 648, pseudogene)
Gene: Small nuclear RNA gene on chromosome X (115,032,427 to 115,032,533, forward strand). Ensembl gene ENSG00000222122.
Homologues: Orthologues: chimpanzee U6 (98% identical), macaque U6 (89% identical). Paralogues in human: RNU6-1209P (84% identical), RNU6-944P (84% identical), RNU6-1091P (81% identical), RNU6-183P (81% identical), RNU6-742P (81% identical), RNU6-744P (81% identical), RNU6-797P (81% identical), RNU6-1243P (80% identical), RNU6-1309P (80% identical), RNU6-218P (80% identical), RNU6-500P (80% identical), RNU6-524P (80% identical), and 1285 more.